SLC2A4 (solute carrier family 2 member 4)
Diseases named in the same sentence as SLC2A4 in open-access papers (continued):
Sharing a sentence is not in itself a finding about the gene and the disease.
diabetes (373 papers, 2006 to 2026). "Numerous studies across diverse regions and ethnic populations have identified correlations between SLC2A4 gene polymorphisms and diseases including diabetes mellitus." (PMID 40854653, 2025). "GLUT4 solute carrier family 2 member 4 (SLC2A4) gene, which encodes glucose transporter 4, is a candidate gene for type 2 diabetes mellitus (T2DM) and also a potential target in cancer treatment." (PMID 37109046, 2023). "Diabetes also reduced the level of GLUT4 (encoded by SLC2A4) that functions as an insulin-regulated facilitative glucose transporter in the heart by 70%." (PMID 34616362, 2021). "In diabetes, the SLC2A4 gene encodes glucose transporters family (GLUTs), which is known as an insulin-sensitive transporter." (PMID 34236536, 2021). "Of note, decreased SLC2A4 expression has been observed in adipose tissue from type 2 diabetic patients and diabetes is increasingly associated with AD." (PMID 27466139, 2016). "SLC2A4 is a glucose transporter whose impairment has again been associated with diabetes mellitus." (PMID 35405953, 2022). "Specifically, both ESR1 and ESR2 regulate blood glucose levels by altering GLUT4 content in tissues through SLC2A4 gene-expression regulation, thereby improving diabetes conditions." (PMID 40508108, 2025). "In sum, we report that diabetes altered miR-29b-3p, miR-29c-3p, miR-199a-5p and miR-532-3p expression in muscle of male rats, where their predicted targets Slc2a4/GLUT4 and Hk2/HK2 are repressed." (PMID 30258406, 2018). "Diabetes reduced Slc2a4/GLUT4 and Hk2/HK2 expression (50–77%), upregulated miR-29b-3p and miR-29c-3p (50–100%), and downregulated miR-93-5p, miR-150-5p, miR-199a-5p, miR-345-3p, and miR-532-3p (~30%) expression." (PMID 30258406, 2018). "As failing and ischaemic hearts have a greater dependence on glycolysis, impaired expression and translocation of SLC2A4 to the sarcolemma due to diabetes could result in an exacerbated reduction in systolic function." (PMID 40759793, 2025). "Epigenetic mechanisms, such as some micro-RNAs and histone post-translational modifications, have already been described to modulate the Slc2a4/GLUT4 expression under diabetes-related conditions, explaining the dissociation between mRNA and protein regulations." (PMID 41150805, 2025). "Studies show that increased H3K9me3 in the Slc2a4 promoter enhancer segment reduces GLUT4 expression in skeletal muscle and worsens glycemic control in diabetes, pointing to H3K9me3 of the Slc2a4 promoter as a potential target for treating diabetes." (PMID 39062577, 2024). "In recent years, we have investigated the estrogen-induced ESR-mediated regulation of SLC2A4/GLUT4 expression, expecting to demonstrate a direct effect of estrogen upon glycemic homeostasis, which could finally be helpful to ameliorate the diabetes condition." (PMID 33430527, 2021). "Additionally, diabetes increased the nuclear factor kappa B subunit 1 protein (p50) expression, a repressor of Slc2a4, which was also predicted as a target for miR-199a-5p and miR-532-3p." (PMID 30258406, 2018). "Hence, reduced GLUT4 expression in skeletal muscle plays a key role in the pathophysiology and treatment of diabetes; and thus, comprehension of mechanisms related to the regulation of SLC2A4/GLUT4 expression is mandatory." (PMID 30258406, 2018). "Diabetes reduced (P < 0.001) by ~55 and ~77% the Slc2a4 mRNA and GLUT4 protein, respectively." (PMID 30258406, 2018). "Higher gene expression levels of LEP, Pomc and Slc2a4 genes and lower levels of the Npy gene in breastfed individuals is in agreement with other epidemiological evidence that breastfeeding might protect against obesity and diabetes." (PMID 28257446, 2017). "In this hypothetical scenario, we may not see association between diabetes susceptibility and SLC2A4 variants because a selective sweep lead to the existence of a small genomic region with no common variants, and the fixed haplotype may be “thrifty”." (PMID 20352120, 2010).
diabetes (continued). "In obesity and type 2 diabetes mellitus (T2DM), the expression of SLC2A4 is selectively decreased in adipocytes." (PMID 30805369, 2019). "Solute carrier family 2 member 4- (SLC2A4-) retinol binding protein-4- (RBP4-) phosphoenolpyruvate carboxykinase 1 (PCK1)/phosphoinositide 3-kinase (PI3K) is an adipocyte derived “signalling pathway” that may contribute to the pathogenesis of type 2 diabetes mellitus (T2DM)." (PMID 30805369, 2019). "Other drugs included insulin used for diabetes, vanadium + aonys in the clinical trial for type 2 diabetes, and alimentary/metabolic disease, targeting INS and SLC2A4, respectively." (PMID 31699147, 2019). "Regarding the insulin-dependent GLUT4, polymorphisms in the SLC2A4 (GLUT4) gene are rare in type 2 diabetes and have the same prevalence among non-diabetic persons, suggesting they are population variants and do not play a role in the aetiology of type 2 diabetes mellitus." (PMID 22698081, 2012). "GLUT4 –coded by SLC2A4 (17p13) is an insulin-sensitive transporter with a critical role in glucose homeostasis and diabetes pathogenesis, preferentially expressed in the adipose tissue, heart muscle and skeletal muscle." (PMID 20352120, 2010). "Expression of Slc2a4/GLUT4 is majorly involved in glucose removal from tissues and, consequently, in glycemic homeostasis, playing an important role in the pathophysiology of diseases such as Type 1 and 2 Diabetes Mellitus and Obesity." (PMID 36735680, 2023). "The insulin resistance signaling pathway is closely related to diabetes, metabolic syndrome and obesity and is also closely related to the activities of phosphoenolpyruvate carboxykinase 1 (PCK1) and solute carrier family 2 member 4/GLUT4 (SLC2A4)." (PMID 35456474, 2022). "In that case, SLC2A4 expression level has no prognostic level for cancer outcome but diabetes and increased insulin secretion have." (PMID 34488531, 2021). "SLC2A4 encodes GLUT4 - a critical player in postprandial glucose disposal, and together this provides evidence for the mechanism underlying the post-challenge specific glycaemic signature seen for SLC2A4 in individuals without diabetes." (PMID 37291194, 2023).
Hyperglycemia (278 papers, 2009 to 2026). An increased concentration of glucose in the blood. "It is well recognized that Slc2a4 knockout induces hyperglycemia, whereas the overexpression of Slc2a4 improves glycemic control even in DM mice, regulations that were directly associated with the amount of GLUT4 at the PM, independently of changes in insulin signaling." (PMID 35011666, 2021). "With the onset of hyperglycemia, the glucose uptake in the adipose tissue and muscles is mostly mediated by GLUT4, an isoform of a family of sugar transporter proteins (encoded on the SLC2A4 gene) containing 12 transmembrane domains." (PMID 30424024, 2018). "In normoxia hyperglycemia we observed significantly increased expression of glucose transporters SLC2A1 (nearly fourfold, p < 0.05) and SLC2A4 (more than sevenfold, p < 0.05) and PKM2 (p < 0.01)." (PMID 35328751, 2022). "What is more critical, in our observations of WWOX KO fibroblasts in comparison to control in normoxia hyperglycemia, we stated that the SLC2A1 and SLC2A4 mRNA increase does not translate into protein level and glucose uptake growth." (PMID 35328751, 2022).
type 2 diabetes (257 papers, 2006 to 2026). "This study presents the first investigation of SLC2A4 (GLUT4) gene variants and their association with type 2 diabetes (T2D) in the Bangladeshi population, identifying rs5435 as a potential risk variant." (PMID 40854653, 2025). "Solute carrier family-2-member-4-gene (SLC2A4) is an insulin-sensitive glucose transporter protein that plays a key regulatory role in the pathogenesis of type 2 diabetes." (PMID 37033267, 2023). "Decreased expression of SLC2A4 in adipose tissue in human obesity and type 2 diabetes has been observed." (PMID 30250736, 2018). "Though Slc2a4 is known to play a major regulatory role in the pathophysiology of type 2 diabetes, emerging evidence suggests that successful pharmacological inhibition of this protein may lead to the development of a novel drug candidate for the treatment of cancer." (PMID 29382080, 2018). "While the study focused on the rs5435 variant of the SLC2A4 gene, it did not investigate other genetic variants involved in insulin signaling or glucose metabolism, which may also contribute to type 2 diabetes (T2D) risk through additive or interactive effects." (PMID 40854653, 2025).
Obesity (237 papers, 2005 to 2026). Accumulation of substantial excess body fat. "That means that higher DNA methylation in the ROI of the Slc2a4 is associated with obesity-related parameters of increased body weight, plasma insulin levels, and blood glucose levels." (PMID 37047391, 2023). "We hypothesized that decreased SLC2A4 gene expression in the VAT of obese humans with impaired glycemic control (high HbA1c) emerges from a fatty-acid-induced (dietary or obesity-associated) increase in DNA methylation in a SLC2A4 enhancer region spanning several SP1 and SREBPF-1 binding motifs." (PMID 37047391, 2023). "DNA methylation was significantly increased at week 2 before Slc2a4 gene expression decreased, which supports our hypothesis that DNA methylation at this region is rather a causative mechanism in regulating Slc2a4 in obesity than a consequential response to high-fat feeding." (PMID 37047391, 2023). "Slc2a4 expression, ChREBP activity, and DNL are decreased in obesity, the underlying cause however remains unidentified." (PMID 37047391, 2023). "Chronic conditions of high fatty acid levels on the other hand, which frequently occur in obesity and are termed lipotoxicity, lead to a decrease in Slc2a4 gene expression in the mouse and cell culture models." (PMID 37047391, 2023). "Slc2a4, Adipoq, mitoNEET, and Tnmd transgenic mice had an equal or even higher degree of obesity than their littermates, but their metabolic profile is healthier." (PMID 36457708, 2022). "KEGG pathway analysis showed that two DEmRNAs, Slc27a1 and Slc2a4, were involved in the insulin resistance signaling pathway, which is closely related to obesity (Yu, Kim & Lee, 2017)." (PMID 30842902, 2019). "Currently, the mechanisms causing the observed downregulation of the SLC2A4 gene in obesity are not known." (PMID 37047391, 2023). "First, we identified gene sets related to the function of each obesity-related serum factor: HG/HI (Insr, Irs1, Rps6kb1, Slc2a4, Slc2a5, Slc2a1), TNF-α (Tnfrsf1a, Tradd, Traf2, Fadd), IL-6 (Il6ra, Il6st, Jak1), and fatty acids (PA, LA, Chol; Ffar1, Ffar4, Ppara, Pdk4, Pgc1a)." (PMID 37047207, 2023). "At the same time, HSD11B1 and SLC2A4 may also be regulated by the corresponding lncRNA and miRNA, which ultimately affects glucose uptake by adipocytes and leads to obesity." (PMID 35456474, 2022). "In addition, obesity was confirmed by decreasing levels of Adipoq, Cebpa and Slc2a4 mRNAs that are known to be inversely correlated to adiposity." (PMID 34608215, 2021). "Similarly, overexpressing Glucose transporter type 4 (GLUT4; also known as SLC2A4) in the adipose tissue induced obesity but with hyperplastic adipose tissue and enhanced glucose tolerance." (PMID 28240264, 2017). "Furthermore, our results showing Slc2a4 overexpression in rodent white adipose tissue are in line with previous observations reporting an increased expression of this gene at the very early stage of obesity." (PMID 29167640, 2017). "Our study revealed that fed late adult mice concurrently with starting obesity demonstrated impaired glucose metabolism including increased plasma insulin levels, decreased glucose tolerance compared to younger mice, and decreased expression of Slc2a4 gene in WAT (compared to early adult mice)." (PMID 29038358, 2017). "The expression of some of these genes, namely CPT1, SLC2A4 and MCP1, were previously shown to be downregulated in the VAT of individuals with obesity." (PMID 36675195, 2023). "MCR1/CD68 ratio increased significantly after weight loss in parallel to adipogenic genes, such as FASN, ADIPOQ, IRS1 and SLC2A4, whereas LEP (an obesity gene marker) and IL6 (an inflammatory marker) decreased." (PMID 23951013, 2013). "Given the reduced insulin sensitivity in the individuals with obesity, we also examined the mRNA levels of Glucose Transporter Type 4 (GLUT4, also known as SLC2A4) gene responsible for glucose uptake in SkM, which was significantly decreased in individuals with obesity." (PMID 40127780, 2025).
Obesity (continued). "We subsequently analyzed publicly available transcriptomic data from VAT of individuals with obesity (GSE20950) who are insulin sensitive (IS) or insulin resistant (IR), to test if there is a further decline of SLC2A4 expression in the combined obese and insulin resistant state." (PMID 37047391, 2023).
Hyperinsulinemia (60 papers, 2010 to 2025). An increased concentration of insulin in the blood. "Also, we for the first time report the relationship between AT SIRT1 and SLC2A4 as well as the tissue-specific effect of hyperinsulinemia on SIRT1 expression." (PMID 29417372, 2018).
metabolic syndrome (54 papers, 2006 to 2026). A cluster of metabolic risk factors for CARDIOVASCULAR DISEASES and TYPE 2 DIABETES MELLITUS. "Seven metabolic syndrome-related genes (CSF3R, TMEM132A, STAB1, VIM, DUOXA1, PILRB, and SLC2A4) were used to construct risk equations." (PMID 37033267, 2023).
breast carcinoma (32 papers, 2013 to 2025). "SLC2A4 and C14orf180 downregulation is linked to poor breast cancer outcomes, with lower expression associated with lower survival." (PMID 39409999, 2024). "Results showed that higher mRNA expression of SLC2A4 and SLC2A11 significantly associated with better prognosis of breast cancer patients (HR: 0.7 [0.55–0.88];p =0.0024 and HR: 0.45 [0.33–0.62];p =5E-07, respectively)." (PMID 34488531, 2021). "Second, the study required more comprehensive and detailed analysis; researching all the gene sets enriched by Metascape will help to explore more potential functions and mechanisms of SLC2A4 in breast cancer." (PMID 34488531, 2021). "High expression of SLC2A4 was significantly correlated with better prognosis in breast cancer patients." (PMID 34488531, 2021). "Results from our study showed that the mRNA expression of SLC2A4 was significantly decreased in BRCA tissues, and high level of SLC2A4-mRNA was significantly relevant to better prognosis in breast cancer patients." (PMID 34488531, 2021). "We further compared DNA hypermethylation in the promoter of SLC2A4 in breast cancer patients to normal samples; data from MethHC showed that there were significant differences between the two groups (p < 0.05)." (PMID 34488531, 2021). "Overall, this result showed that SLC2A4 is a potential prognostic biomarker for breast cancer patients." (PMID 34488531, 2021). "Prognostic values of SLC2A4 in breast cancer patients with different cancer stages were also investigated by using UALCAN." (PMID 34488531, 2021). "The inhibition of SLC2A4 could compromise cell proliferation and metastasis in breast cancer, prostate cancer, and gastric cancer." (PMID 36866237, 2023). "In summary, the results indicated that SLC2A4 may be exploited as the most useful biomarkers of SLC2s for prediction of breast cancer patients’ survival." (PMID 34488531, 2021). "According to the data from public-omicsrepository, SLC2A4 (GLUT4) was found to be significantly downregulated in most cancers, and higher messenger RNA (mRNA) expression of SLC2A4 significantly associated with better prognosis of breast cancer (BRCA) patients." (PMID 34488531, 2021). "The expression level of SLC2A4 in breast cancer tissues was lower than that in normal samples." (PMID 34488531, 2021). "In addition, SLC2A4 may play an important role in breast cancer, including AMPK pathway, glucose homeostasis, and protein localization." (PMID 34488531, 2021). "Compared with normal tissues, SLC2A4 was significantly downregulated in patients with all subtypes and stages of BRCA, and high level of SCL2A4 in luminal A breast cancer and stage III breast cancer can significantly predict better prognosis." (PMID 34488531, 2021). "SLC2A4 encodes a protein that functions as an insulin-regulated facilitative glucose transporter; inhibition of this gene affects cell proliferation and cell viability, suggesting a potential biological hypothesis for how ACAP1 may be involved with breast cancer." (PMID 28362817, 2017).
cardiac hypertrophy (29 papers, 2009 to 2024). "Fatty acid oxidation (Acadm, Etfdh, Acadl, Acadvl, Eci1, Hadh, Phyh, Acaa2, Hadha, Hadhb, Cd36), glucose metabolism (Dld, Pdha1, Pgam1, Pgam2, Acss1, Ldhb, Fh1, Slc2a4, Aldh6a1), TCA cycle (Aco2, Dld, Fh1, Ogdh, Sucla2, Sdha, Idh3b, Idh2) were up-regulated by hispidulin in cardiac hypertrophy." (PMID 33324687, 2020).
Hypoglycemia (23 papers, 2013 to 2025). A decreased concentration of glucose in the blood. "Moreover, in the context of hypoglycemia observed in Mir137−/−, the expression level of Slc2a4 (Glut4), a glucose transporter involved in carbohydrate metabolism and modulated by GH/GHR signaling, was also reduced." (PMID 40598150, 2025).
hypothyroidism (13 papers, 2014 to 2025). Abnormally low levels of thyroid hormone. "Vice versa, we have previously shown that hypothyroidism leads to reduced glucose uptake and correspondingly low Slc2a4 expression in bone tissue in mice." (PMID 38719881, 2024).
gastric cancer (11 papers, 2007 to 2026). A primary or metastatic malignant neoplasm involving the stomach. "According to the latest cancer epidemic trend from China National Cancer Center, we also investigated the relevance between the expression and prognosis of SLC2A4 in lung cancer, liver cancer, and stomach cancer." (PMID 34488531, 2021).
lung carcinoma (10 papers, 2007 to 2025). "The most relevant GLUTs in cancer include GLUT1 (SLC2A1), GLUT3 (SLC2A3) and GLUT4 (SLC2A4), which are highly expressed in breast, CRC and lung cancers, with a high affinity for glucose and commonly associated with poor prognosis and therapy resistance." (PMID 41154605, 2025). "Neither GLUT-3 nor GLUT-4 is positively stained in normal lung epithelia while lung cancers have elevated levels of SLC2A3 and SLC2A4." (PMID 36518662, 2022).
prediabetes (10 papers, 2017 to 2025). "In humans, although some pioneering studies reported that SLC2A4/GLUT4 expression was unchanged in skeletal muscles of prediabetes and T2DM subjects, other studies reported a reduction of GLUT4, which was further confirmed in more sensitive quantitative analyses of GLUT4." (PMID 28428964, 2017).
Sepsis (9 papers, 2014 to 2025). Sepsis is defined as life-threatening organ dysfunction caused by a dysregulated host response to infection. "Gene expression of glucose transporter GLUT1 (Slc2a1), but not GLUT4 (Slc2a4), was upregulated in acute and prolonged sepsis." (PMID 39821755, 2025).
intrauterine growth restriction (6 papers, 2013 to 2022). "In addition, upregulation of miR-29a-3p was observed in skeletal muscle of rats with intrauterine growth restriction; and overexpression of miR-29a-3p in muscle C2C12 cells induced a reduction in Slc2a4 mRNA and GLUT4 protein." (PMID 28428964, 2017).